ENSG00000279983 (novel protein)
Gene: Protein-coding gene on chromosome 5 (141,223,372 to 141,245,861, forward strand). Ensembl gene ENSG00000279983.
Genetic constraint (gnomAD): Loss-of-function variants: 3 observed, 1.09 expected, observed/expected ratio (o/e) 2.74. That is too few expected variants to judge how well the gene tolerates losing a copy. Missense variants: 14 observed, 14.11 expected, observed/expected ratio (o/e) 0.99, 90% interval 0.65 to 1.54. Synonymous variants: 8 observed, 5.75 expected, observed/expected ratio (o/e) 1.39, 90% interval 0.78 to 1.91.